IL13 (interleukin 13)
Diseases named in the same sentence as IL13 in open-access papers (continued):
Sharing a sentence is not in itself a finding about the gene and the disease.
eosinophilia (continued). "Taken together, lower TGF-β1 levels in lungs with NP-CpG may be a consequence of lower eosinophilia and Th2-related cytokine production (IL-4, IL-5, IL-13) in NP-CpG treated mice." (PMID 26387548, 2015). "Interestingly, the same studies showed IL-4 and IL-13 to be potent inducers of airway eosinophilia, whereas in our study, airway hyporesponsive, highly eosinophilic OVA/CFA sensitized mice had comparatively lower BAL fluid levels of both cytokines." (PMID 25123451, 2014). "Pre-treatment with parasite-derived exosomes before Alternaria extract administration led to a sharp reduction in bronchoalveolar lavage eosinophilia, and suppressed expression of the Type 2 cytokines interleukin (IL)-5 and IL-13 by innate lymphoid cells (ILCs)." (PMID 25421927, 2014). "The stronger increase in ILC2 numbers in the absence of IL-1β following Hp infection could be confirmed by pharmacological blockade with Anakinra, and Anakinra treated mice additionally exhibited increased eosinophilia and IL-5 and IL-13 cytokine levels." (PMID 23935505, 2013). "Dysregulated type 2 immunity in allergic asthma is characterized by an expansion of CD4+ Th2 cells and cytokines (IL-4, IL-5, IL-13), elevated total and allergen-specific IgE, eosinophilia, and airway inflammation and a counterbalance emergence of B1a cells with regulatory capacity." (PMID 23840604, 2013). "Previous studies have also demonstrated that eosinophilia occurs between the 5th and 7th weeks after exposure to the parasite and may be induced by Th2 cytokines, such as IL-4, IL-10, IL-13, IL-9, and especially IL-5." (PMID 23401741, 2013). "We hypothesize that MA and MA128 and CsA prevent AHR by downregulating eotaxin, IL-5 and IL-13 expression and, in so doing, by reducing eosinophilia." (PMID 22203879, 2012). "Increased mucus and airway eosinophilia in FI-RSV mice were associated with increased expression of IL-13 in the lungs; which was not present in NE-RSV vaccinated mice." (PMID 21789184, 2011). "Taken together, the observed reduction in airway eosinophilia by artesunate may be a result of combined inhibitory effects on IL-4, IL-5, IL-13, eotaxin and RANTES production, and on adhesion molecule expression, secondary to inhibition of PI3K/Akt." (PMID 21695271, 2011). "The effect of anti-IL-13 treatment on mechanism-based endpoints, for example inhibition of airway eosinophilia, are important for understanding the pharmacology of anti-IL-13 mAb and are findings consistent with IL-13 stimulating local production of the eosinophil chemoattractant eotaxin." (PMID 20957211, 2010). "Allergic asthma is caused primarily by an inappropriate CD4+ Th2 response, which results in symptoms mediated by Th2 cytokines, including IL-13 provoking airways hyperresponsiveness and mucus production, IL-4 promoting the production of antigen specific IgE, and IL-5 inducing eosinophilia." (PMID 20659336, 2010). "Eosinophilia is driven by Th2 cytokines (e.g., IL-4, IL-5, IL-13) produced by Th2 cells." (PMID 19657453, 2009). "IL-4 and IL-13 are critically involved in the pathogenesis of allergic asthma by regulating IgE-production by B cells, inducing airway hyperreactivity and triggering key features of airway remodeling, whereas IL-5 is a key factor for eosinophilia." (PMID 18724870, 2008). "In this case, the marked elevation of anti-Dsg1, eosinophilia, and dermal eosinophilic infiltrate suggest that IL-17A inhibition may have downregulated the Th1/Th17 axis, relieving inhibition of Th2 cells and promoting IL-4/IL-13 elevation." (PMID 41000395, 2025). "Notably, eosinophilia was disfavored in the absence of IL-22, a phenomenon that was associated with less IL-13 production." (PMID 39635124, 2024).
eosinophilia (continued). "Type 2 inflammation is associated to a greater disease burden and is defined by tissue eosinophilia (≥ 10 eosinophils/high field power, blood eosinophilia (≥ 150 cells/μL and high level of serum total IgE (≥ 100 KU/L) and additional increased expression of T2 cytokines such as IL-4, IL-5, IL-13." (PMID 38913122, 2024). "Indeed, L.rhamnosus supplementation inhibited the lung eosinophilia (with no impact on neutrophil and lymphocyte numbers) and the Th2-associated mRNA transcripts (i.e., Il4 and Il5 and a trend for Il13) in mice neonatally sensitized with OVA." (PMID 36685549, 2022). "IL-13 creates a typical Th2 milieu in the lungs which favors the propagation of chronic inflammatory disorders and mediates exhibition of characteristic allergic hallmarks such eosinophilia, mucous cell metaplasia, immunoglobulin E production, airway hyperresponsiveness and fibrosis." (PMID 34418598, 2021). "Impaired tissue homing might be the cause for blood eosinophilia, as migration of eosinophils to tissues, but not their bone marrow egress or production, is dependent on IL-4/IL-13-induced eotaxins and vascular-cell adhesion molecule-1." (PMID 32344789, 2020). "Eosinophilic bronchitis is usually a Type 2 (T2)-driven process and therefore a sputum eosinophilia of greater than 3% usually indicates a response to treatment with corticosteroids or novel therapies directed against T2 cytokines such as IL-4, IL-5, and IL-13." (PMID 29018800, 2017). "In addition, substantial evidence exists from in vitro cell culture models, in vivo animal models and observational human studies for the role of IL-13 (and IL-4) in driving eosinophilia and type 2 inflammation, which led to interventional studies targeting these pathways in human disease." (PMID 29034234, 2017). "Furthermore, IL-13 has been shown to downregulate junctional components including E-cadherin in bronchiolar epithelial cells leading to disruptive effects on airway epithelial barrier function and explaining why we see stronger eosinophilia upon IL-13 treatment." (PMID 27917175, 2016). "Therefore depletion of CD8+ T lymphocytes may partly reduce airway eosinophilia as a consequence of a reduction in IL-13, since it has been reported that administration of IL-13, or overexpression of IL-13 in the airways, induces eosinophilia." (PMID 16740158, 2006). "Following challenge with np-Der p1 protein, immunized mice exhibited reduced allergic responses, including lessened eosinophilia, decreased Th2 (GATA3+ and IL-5+IL-13+) and Th17 (IL-17A+) cell frequencies, and lowered mucus production." (PMID 40985871, 2025). "The transient eosinophilia did not appear to predict worse clinical outcomes, but it reflects the complex immune modulation when IL-4/IL-13 is blocked, as the latter effect could potentially cause eosinophils to temporarily redistribute from the tissues to blood." (PMID 40843371, 2025). "This was evidenced by elevated levels of IL-5, IL-13, and CCL11; enhanced eosinophilia; and higher numbers of total cells, lymphocytes, macrophages, and neutrophils in the BALF." (PMID 40587812, 2025). "Itepekimab, an anti-IL-33 antibody, effectively engages its target and mitigates tissue eosinophilia, while CM310-stapokibart, tralokinumab, and lebrikizumab inhibit IL-4/IL-13 signaling with variable efficacy depending on patient biomarkers." (PMID 40732309, 2025). "Inflammation with eosinophilia is regulated by the chemokines CCL11 and the cytokines IL-13, IL-5, and IL-33." (PMID 36970065, 2023). "RSV driven IL–33–activated ILC2 is crucial for the development of airway inflammation, including eosinophilia and airway hyperreactive response, through ILC2–specific IL–13 production." (PMID 35603159, 2022). "ILC2s boost airway eosinophilia via IL-5 production and enhance AHR, goblet cell hyperplasia and Th2-mediated AAI through IL-13 secretion." (PMID 36305904, 2022).
eosinophilia (continued). "The protective effect of Hp‐TGM on airway eosinophilia was also obtained in the longer T‐cell mediated models of HDM or OVA sensitisation with significant inhibition of eotaxin‐1, IL‐4 and IL‐13 responses depending on the model and time‐point." (PMID 35758054, 2022). "Interestingly, L.rhamnosus maternal supplementation resulted in decreased eosinophilia and neutrophilia in the bronchoalveolar lavage (BAL) fluid and in decreased Th2-associated cytokines mRNA transcripts (i.e., Il4, Il5 and Il13) in the lung of neonatally sensitized mice." (PMID 36685549, 2022). "Allergic asthma is characterized by elevated levels of IgE antibodies, type 2 cytokines such as interleukin-4 (IL-4) and IL-13, airway hyperresponsiveness (AHR), mucus hypersecretion and eosinophilia." (PMID 33976140, 2021). "In addition, IL-13, which may induce eosinophilia in the lung depends largely on IL-5." (PMID 34625911, 2021). "Studies have also shown that RSV driven IL-33-activated ILC2 were crucial for the development of airway inflammation, including eosinophilia and AHR, through ILC2-specific IL-13 production." (PMID 33953732, 2021). "We demonstrate that vaccination against IL-4 and IL-13 is well tolerated and protects against key features of chronic asthma in mice, including AHR, eosinophilia, and mucus overproduction, after both prophylactic or therapeutic vaccination protocols." (PMID 33976140, 2021). "IL13 is a central mediator of allergic asthma and its blockade in mice upon HDM exposure reduces eosinophilia in BALF, peribronchial collagen, and goblet cell hyperplasia." (PMID 33942458, 2021). "In nasal epithelial cells, IL-13 upregulates ALOX15 and promotes eoxtaxin 3 expression, likely promoting tissue eosinophilia in CRSwNP patients." (PMID 32292784, 2020). "GMP administration significantly decreased IL-5, IL-13 and GATA3 expression in the intestinal tissue of FA animals, which is in accordance with reduced eosinophilia, goblet cell hyperplasia and IgE gene expression in small intestine of GMP treated rats." (PMID 32992996, 2020). "Administration of anti-IL-13 antibody markedly decreased STAT6 phosphorylation in the lung, BAL eosinophilia, and goblet cell hyperplasia." (PMID 31866859, 2019). "Accordingly, there was increased expression of Muc5ac, pro-Th2 and Th17 cytokine (e.g., Il13, Il33 and Il17a), increased BALF eosinophilia, as well as increased genes involved in epithelial repair responses in the lungs (e.g. Egfr and Tff2)." (PMID 31089182, 2019). "Lack of IL-25, TSLP, and IL-33 resulted in normal lung ILC2 accumulation, but reduced secretion of IL-5 and IL-13 which lead to reduced AAM and eosinophilia." (PMID 29696023, 2018). "Recombinant HpARI co-administration with Alternaria allergen abrogated BAL eosinophilia and lung ILC2 IL-5 and IL-13 production, 24 hr later, again replicating the effects observed with total HES." (PMID 29045903, 2017). "There was a positive correlations between sputum HMGB1 expressions in sputum eosinophilia and sputum TNF-a, IL-5 and IL-13 levels." (PMID 28630596, 2017). "In vitro studies found that IL-13 upregulates IL-5, CCL26, and other related cytokines that contribute to eosinophilia." (PMID 29034234, 2017). "On the other side, depletion of macrophages before allergen/rhinovirus challenge lead to reduced eosinophilia, CCL11 and IL-13 levels." (PMID 24612750, 2014). "Intratracheal administration of LY294002 reduced OVA-induced increases in total cell counts, eosinophil counts, and IL-5, IL-13, and CCL11 (eotaxin) levels in BAL fluid and dramatically inhibited OVA-induced tissue eosinophilia and airway mucus production." (PMID 23690670, 2013). "Th2-high subjects had greater expression of IL-13 in bronchial biopsies along with greater AHR and higher serum IgE, blood and airway eosinophilia." (PMID 24032029, 2013).
eosinophilia (continued). "The improved pathology correlated with a decrease in IL-13 production by lamina propria cells, a decrease in the production of other type-2 cytokines by MLN cells, and a decrease in blood eosinophilia and IgE." (PMID 22539101, 2012). "Neonatal RSV infection followed by adult exposure to allergen resulted in significantly higher lung resistance, along with increased total cellularity, eosinophilia, and increased TNF-α and Th2 cytokines (IL-5 and IL-13) in BALF." (PMID 16893457, 2006). "Surprisingly, concentrations of canonical Type 2 cytokines IL-4, IL-5, and IL-13 were highest in the primary infection mice, despite the lack of eosinophilia." (PMID 41190814, 2025). "Furthermore, assessment of the ratio of eosinophilia in BAL cells and levels of Th2-type cytokines, including IL-5 and IL-13 in BAL fluid, showed a more marked increase in SLPI KO mice than in WT mice." (PMID 40546642, 2025). "Combinations of the type-2interleukins (IL)-4, IL-5, IL-9 and IL-13 promote immune effector functions includingantibody isotype switching to IgE, adaptive T helper 2 (TH2) cellpolarization, eosinophilia, mast cell hyperplasia, goblet cell hyperplasia and tissuerepair." (PMID 38935708, 2024). "We demonstrate that IL-13-mediated eosinophil infiltration depends on TRAIL and MID-1 and that MID-1-knockdown completely ablated eosinophilia and eotaxin-1 production, unlike TRAIL deficiency." (PMID 38026128, 2023). "A negative correlation with tissue eosinophilia can also be observed in the case of IL-13, the concentration of which, similarly to IL-5, significantly increases in the serum after treatment." (PMID 34203871, 2021). "Consistent with the degree of eosinophilia, the BALF levels of eosinophil recruitment-associated cytokines were significantly elevated in IL-13-treated WT but not in IL-13-treated mye-IL4Rα−/− mice." (PMID 34326406, 2021). "PD-L2 blockade at the time of allergen challenge, but not at sensitization, increased AHR and eosinophilia, in addition to IL-5 and IL-13 production, but reduced IFN-γ production in the lungs and lymph nodes." (PMID 33968057, 2021). "Our present study illustrates that whereas a muted eosinophil response is evident in the absence of IL-4/IL-13 signaling, low eosinophilia is still an integral component of immune attrition to juvenile adults in IL-4Rα mice." (PMID 32571840, 2020). "It was reported that oxymatrine and taraxasterol could reduce the production of IL-4, IL-5, and IL-13 in bronchoalveolar lavage fluid and OVA-specific IgE in sera and inhibit OVA-induced eosinophilia in lung tissues." (PMID 28751921, 2017). "Administration of anti-IL-13 resulted in decreased BAL eosinophilia compared to control, however, there was concomitant upregulation of blood eosinophils in the anti-IL-13-treated mice but not in the controls." (PMID 29034234, 2017). "Then in AAD we identified inductive roles for: TLR2 in IL-5 release from MLN T cells, IL-5 and IL-13 release from splenocytes and AHR; TLR4 in eosinophil infiltration into BALF and blood (partial) and AHR, and; MyD88 in blood eosinophilia, IL-13 release from MLN T cells and AHR." (PMID 27309732, 2016). "Together, these reports suggest that ILC2-derived IL-5 and IL-13 contribute nonredundantly to eosinophilia." (PMID 26965110, 2016). "The Th2 cytokines IL-4 and IL-13 bind to the IL-4/IL-13R to activate STAT-6, which plays a major role in mediating a variety of phenotypic endpoints in allergic airway inflammation, including eosinophilia, mucous cell metaplasia, and airway fibrosis." (PMID 26091108, 2015). "In this study, our protocol was shown to mimic prototypical characteristics of clinical atopic asthma, namely blood, tissue and BALF eosinophilia, an elevation of TH2 cytokines IL-5 and IL-13 in BALF, and prominent AHR, as shown by a heightened reactivity to methacholine." (PMID 25089623, 2014). "Airway eosinophilia and IL-13 production were augmented by poly IC in Kit+/+ mice but not in KitW/KitW-v mice." (PMID 23452625, 2013).
eosinophilia (continued). "Further, IL-25 administered to RAG1 knockout mice that lack B or T cells led to eosinophilia and increased tissue IL-5 and IL-13 expression suggesting that a non-B/non-T cell population was active in vivo." (PMID 24876829, 2013). "Taken together, we speculate that inhibition of NF-κB activation directly or indirectly attenuated IL-5, IL-13, eotaxin, RANTES, TNF-α, and TGF-β gene expression, eosinophilia infiltration, mucus production, collagen deposition, and allergic lung inflammation." (PMID 22675381, 2012). "In fact, STAT6 knockout mice have no response to IL-4 and IL-13, do not develop Th2 cells in response to IL-4, fail to produce IgE, airway hyperresponsiveness and bronchoalveolar lavage eosinophilia following allergen sensitisation." (PMID 22401596, 2012). "Thus it appears that while IL-4/IL-13 signaling through IL-4Rα and STAT6 is essential for induction of AAM genes, lung inflammation and eosinophilia are only partially dependent on this pathway." (PMID 22014099, 2011). "Furthermore, while IL-4/IL-13 signaling through IL-4Rα and STAT6 is essential for AAM protein expression, lung inflammation and eosinophilia are only partially dependent on this pathway." (PMID 22014099, 2011). "As blocking IL-4 and IL-13 does not influence eosinophil maturation and release from the bone marrow, dupilumab likely traps eosinophils in the blood compartment, which in some patients will manifest eosinophilia." (PMID 40863432, 2025). "Likewise, biologics against the IL-4 and IL-13 signaling pathways have failed to improve symptoms, although they successfully treat eosinophilia." (PMID 39962262, 2025). "In conclusion, we showed that IL-13 can be depicted in the serum of severe asthmatic patients and may reflect peripheral eosinophilia in patients without systemic steroid use." (PMID 36326393, 2022). "In comparison, trehalose did not affect LPS‐mediated upregulation of CD69 on mouse blood eosinophils and mRNA levels of IL‐5 and IL‐13 in human eosinophilic cell line, suggesting that trehalose may not directly act on eosinophils to alleviate eosinophilia." (PMID 35988262, 2022). "Furthermore, IL‐5 and IL‐13 are important CD4 T‐cells and ILC2‐derived cytokines that are involved in eosinophilia, mucus production, and airway hyperreactivity, and they have been suggested as biomarkers and therapeutic targets for type‐2 inflammation‐related disorders such as allergic asthma." (PMID 34873877, 2022). "Suppression of eosinophilia was marked, both when Hp‐TGM was given at the time of sensitization, or during repeated challenge, and again we found significant inhibition of eotaxin‐1, IL‐4 and/or IL‐13 responses, depending on the model and the time‐points examined." (PMID 35758054, 2022). "Of note, neither PCTR1 nor PD1 increased Il-13 expression or eosinophilia." (PMID 34489955, 2021). "Besides, our synbiotic, TP, and LGG strongly down-regulated eosinophilia, IL-5, CCL17, IL-13." (PMID 32582180, 2020). "In addition, independent of eosinophilia, IL-13 induces tissue remodeling by promoting collagen deposition, angiogenesis, and epithelial hyperplasia." (PMID 33008138, 2020). "Specifically targeting DCs to modulate CD4+ T cell responses may represent a promising approach to treat allergic asthma where an enhanced Th2 response frequently leads to IgE production (IL-4), eosinophilia (IL-5), mast cell activation (IL-9), and AHR (IL-13)." (PMID 28439267, 2017). "Thus, those asthmatics in this phenotype with high levels of predictive biomarkers such as eosinophilia and FENO may well respond to therapies targeting IL-13 biology and/or eosinophilic inflammation." (PMID 27978840, 2016).